IFNG (interferon gamma)
Diseases named in the same sentence as IFNG in open-access papers (continued):
Sharing a sentence is not in itself a finding about the gene and the disease.
tumor (continued). "Univariate analyses revealed that the baseline bone marrow tumor burden, CRS severity, several serum biomarkers (including max lg CRP, IL-10, IFNγ, ferritin, and D-dimer levels), and the usage of tocilizumab/corticosteroids were statistically associated with the incidence of severe cytopenia." (PMID 34277448, 2021). "PD-1 and CTLA-4 are expressed on T cells during priming and activation, while in the tumor microenvironment (TME), local interferon-gamma (IFNγ), mainly derived from effector lymphocytes, induces the expression of PD-L1 on cancer cells and intra-tumoral immune cells." (PMID 33541368, 2021). "Moreover, the expression of IFNγ and CD127, two canonical NF-κB-dependent genes, are required for tumor clearance upon CTLA-4/PD-1 dual blockade." (PMID 33572260, 2021). "After subtracting background levels of IFNγ production in wells containing no tumour cell antigen, we observed an increase in tumour-specific IFΝγ production from cells in the tumour-draining lymph node." (PMID 34784792, 2021). "However, both AURKA and AURKB expression were significantly inversely correlated with markers for T-cell infiltration of the tumor: CD3E, CD4, CD8A, LCK, PDCD1 and IFNG." (PMID 33123754, 2021). "Lymphocytes isolated from the spleens of tumor-bearing mice with different treatments were co-cultured with either xenogeneic urothelial cells or MBT-2-luc cells, and co-cultured conditioned medium were collected assayed for IFNγ activation in by ELISA." (PMID 33156394, 2021). "No significant change in total CD8+ T cells was observed in the tumor microenvironment, but CD8+IFNγ+ T cells were observed to significantly increase in IRF3KO mice, suggesting that macrophages downregulated the presence of tumor infiltrating CD8+IFNγ+ T cells." (PMID 34768716, 2021). "Next, we examined the ability of SFV virus-derived IFNg (vdIFNg, a supernatant from the cells infected with SFV/IFNg) to polarize macrophages to an M1-like tumor-suppressive phenotype and the ability of these M1 macrophages to inhibit 4T1 spheroid growth in a 3D model." (PMID 34835178, 2021). "To substantiate the ability of the analysis pipeline for spatial subanatomical expression analysis, we sought to analyze the effect of tumor antigen expression on the spatial expression of effector gene GZMB and IFNγ and the spatial datasets were divided into a CD19high and CD19low area." (PMID 34155235, 2021). "CDX-527 was demonstrated to have potent T-cell activation by increasing IL-2 and IFNγ production and anti-tumor activity to CD27-expressing lymphoma cells in an immunodeficient mouse model, with comparable anti-tumor activity to separate CD27 agonizing and PDL1 inhibiting monoclonal antibodies." (PMID 34630390, 2021). "The Th1 subtype produces large amounts of IFNγ, a cytokine that suppresses tumor growth by promoting proliferation and differentiation of CD8 + cytotoxic T cells and enabling the priming of APCs against tumor antigens." (PMID 34095125, 2021). "Using both syngeneic and athymic mice, we showed that in the absence of CD8+ T cells, tumor levels of GM-CSF and IFNγ were drastically reduced, with TAMs no longer able to efficiently polarize to M1-like." (PMID 34446712, 2021). "Intriguingly, RA supplement dramatically inhibited the tumor-promoting capacity of IL-17 and IFNγ transformed TA-MSCs, which had 68% reduction in tumor weight and 53% reduction in tumor volume compared to TA-MSCs without RA treatment." (PMID 33889575, 2021). "Another favorable characteristic of memory NK cells is represented by the fact that the enhanced capability to produce cytokines, particularly IFNγ, is under the control of CD16-initiated signals, thus strictly dependent on the availability of the tumor-targeting mAb." (PMID 34065399, 2021). "G47Δ treatment of a syngeneic bilateral hepatoma model inhibited both injected and non-injected tumors, increased tumor-specific IFNγ splenocytes in vitro, and significantly increased CD8+ but not CD4+ T cells." (PMID 34578321, 2021).
tumor (continued). "Moreover, we identified the IFNγ-CXCL10 axis as being one of the drivers of TCB-mediated T cell infiltration in tumors, whereby IFNγ released by activated T cells induces CXCL10 secretion, which in turns attracts CXCR3-expressing T cells into the tumor sites." (PMID 33406104, 2021). "All tumor-irradiated Sirpα−/− mice developed inflammatory responses with an elevated serum level of cytokines TNFα, IL-1β, IL-12, and IFNγ, whereas WT mice treated with the same RT regimen did not exhibit similar increases in cytokines." (PMID 34050181, 2021). "Acetate could also support histone acetylation and IFNγ production in CD8+ T cells under conditions of glucose restriction, mimicking the tumor microenvironment." (PMID 33679780, 2021). "Primary OT-I Tg CD8+ T cells transduced with mPD-1 were further tested for the reduction of IFNγ production after stimulation with H-2Kb-expressing tumor cell line, EL-4 cells, with or without mPD-L1 or mPD-L2 expression." (PMID 33990697, 2021). "Most of the IL-12-induced effects are mediated by the secretion of interferon gamma (IFNγ), which itself exerts cytostatic and antiangiogenic activities and upregulates the major histocompatibility complex (MHC) I and MHC II expression on tumor cells for enhanced recognition and lysis." (PMID 34684032, 2021). "“Hot tumours” describe those where the cytotoxic lymphocytes (CTLs) are infiltrated and inflamed, showing high expression of activation marks such as PD1 and PDL1, with increased IFNγ and granzyme B, and a low stromal component (CMS1 subtype)." (PMID 33669775, 2021). "Besides IFNγ-mediated upregulation of IDO expression in mDCs, tumor cells promote mDC tolerization in the tumor microenvironment via paracrine Wnt-mediated signaling." (PMID 33072086, 2020). "Since IFNγ and IL-17A do not directly kill tumor cells (not shown), these data suggest that the increase in cytotoxic factors is responsible for tumor cell killing." (PMID 33042110, 2020). "Similarly, for the representative values of the expression levels of genes involved in tumor-T cell interaction, we selected six genes (IFNGR1, PD-L1, CXCL9, IFNγ, PD-1, and CXCR3) and termed this group as an immune response predictor (IRP)." (PMID 32795913, 2020). "Alternatively, well-known agents targeting IFNG, IL2, or TLR9 might be considered as adjuncts in tumor types already demonstrating the T cell-inflamed phenotype." (PMID 33106165, 2020). "Such an increase in IFNγ is associated with a more effective immune response and an increased in fibronectin, an ECM protein involved in the development of a non-permissive tumor environment." (PMID 33138017, 2020). "Indeed, we found that the administration of IFNγ resulted in STAT1 phosphorylation and directly increased tumor PD-L1 expression." (PMID 32079180, 2020). "Importantly, tumor-infiltrating CD8+ T cells in SMF-treated mice produced more antitumor granules and cytokines, including granzyme B, IFNγ and TNFα, than their counterparts from control mice." (PMID 32884074, 2020). "This could bring together T cells secreting notable amounts of IFNγ, TGBβ, IL32, and IL18RAP with myeloid/monocyte-derived cells in the tumor microenvironment." (PMID 33076479, 2020). "Additionally, IL‐1β release from dendritic cells was shown to be essential for priming of interferon gamma (IFNγ)‐producing CD8+ T cells and elimination of tumor cells." (PMID 32770571, 2020). "When investigated, ferroptosis in CD8 + T cells that is activated by cancer immunotherapy, the interferon-gamma (IFNγ), downregulates the expression of SLC3A2 and SLC7A11, impairs the uptake of cystine by tumor cells, and as a consequence, promotes tumor cell lipid peroxidation and ferroptosis." (PMID 32372896, 2020). "In addition, the activated OT1-iT cells secreted comparable levels of IFNγ and GzmB to OT1-T cells, indexing their tumor-eradicating behavior." (PMID 32669292, 2020).
tumor (continued). "Antagonizing ZAP-70 inhibition by siRNA against Rasal1 increased the number of CD8+ tumor-infiltrating T-cells expressing granzyme B and interferon gamma (no ‘1') and enhanced tumor killing." (PMID 33194762, 2020). "Thereby secretion of measurable amounts of IFNγ was only observed when UniCAR 28/ζ NK-92 cells, tumour cells and α-GD2 TMs were combined, whereas no release of IFNγ was found in the absence of TMs." (PMID 32034289, 2020). "IFNγ activates direct cytostatic effects on cancer cells, as well as triggers a cytotoxic response from CD8 T cells and NK cells, perhaps the most important immune anti-tumor activity." (PMID 32722549, 2020). "Inflammation in the tumor microenvironment and production of inflammatory cytokines such as TNF-α, IL-1β, and IFNγ (that could also be induced by HCMV) may lead to further induction of PRLR." (PMID 32121009, 2020). "IFN-γ signaling in tumor cells directly activates apoptotic processes, but non-specificity of IFNG/IFNGR interaction increases the chance for side effects." (PMID 33005420, 2020). "We demonstrated that the Immunity High subtype is associated with increased immune scores, stromal scores, HLA genes, immune checkpoint molecules, Th1/IFNγ gene signature, and the highest infiltration of CD8+ T cells, and decreased tumor purity and m6A RNA methylation." (PMID 32346613, 2020). "Further, Mn2+-treated E.G7-bearing mice showed obviously reduced tumor size with significantly increased IFNγ-producing CD8+ TILs, and specifically more SIINFEKL+CD8+ TILs, indicating the enhanced tumor antigen-specific recognition and increased antigen-specific CTLs." (PMID 32839553, 2020). "In continuation to our previous research in understanding the mechanism of NLGP mediated tumor growth restriction, we have reported that therapeutic NLGP treatment significantly reduces the availability of VEGF in tumor hosts, in an immune dependent (CD8+ T cells and IFNγ) manner." (PMID 32211322, 2020). "Finally, we investigated the connection between tumor grades and hub genes, in which LCK, CD2, CD3D, IFNG, CD8A, and CCL5 showed significant correlation with different tumor grades (p < 0.05), with grade increase corresponding to increased gene expression." (PMID 32081834, 2020). "Killing of IFNγ pre-treated human target cells by PD-L1 CAR haNKs was durable as no tumor cell growth rebound was observed." (PMID 32633234, 2020). "This adaptive tumor resistance mechanism uses large quantities of IFNγ from the tumor microenvironment: such a negative feedback loop induces PD-L1 expression on the tumor cell surface, which in turn suppresses PD-1+ TLs activity." (PMID 33381116, 2020). "In this study, a higher percentage of SHP-1–/– CD8 T cells secreted IFNγ and TNFα, which might be one of the mechanisms by which SHP-1–/– CD8 T cells were able to eliminate tumor cells more efficiently." (PMID 33425916, 2020). "Furthermore, moDCs in αPD1 treated patients show enrichment for genes related to effective anti-tumor immunity, including MHC class II antigen presentation, interferon gamma signaling and CD28 co-stimulation." (PMID 32690667, 2020). "There was a shift towards immature NK cell populations in leukemic BM, and we did not detect subpopulations with high BHLHE40 or IFNG (IFNγ) expression that would characterize active tumor killing, matching targets inhibited by TGF-β." (PMID 33218352, 2020). "Interferon-gamma treatment of tumor cell lines did not significantly alter recognition and killing by VGLL1 CTLs." (PMID 33087697, 2020). "We found that several tumor-specific CD8+ T cell clones did not transcribe nor produce IFNγ upon T cell activation, correlating with CpG hypermethylation at the IFNγ promoter, particularly at transcription factor binding sites." (PMID 32194559, 2020).
tumor (continued). "Collectively, the results presented here suggest that G007-LK-induced blockade of WNT/β-catenin signaling leads to improved efficacy of PD-1 immune checkpoint blockade, and in addition induction of an IFNγ and CD8+ T cell-dependent anti-tumor-immune response against B16-F10 tumors." (PMID 32332858, 2020). "In addition, expression of IFNγ was also measured in CD4+ T cells and in NK cells in the spleen and tumor." (PMID 33584714, 2020). "Activated CTLs secrete several cytokines such as interferon-gamma (IFN-γ), tumor necrosis factor-alpha (TNF-α) and the crucial cytolytic mediators (perforin, granzyme, etc.), which improve antigen presentation and mediate anti-tumor effects." (PMID 33333816, 2020). "Tumor cells express PD-L1 and secrete CXCL9 upon IFNγ receptor binding to IFNγ." (PMID 32795913, 2020). "In colon cancer, expression profile of immune-related genes (e.g., IFNG, IL15, GNLY, CCL3, CXCL16) together with infiltration of the tumor with cytotoxic and memory lymphocytes (“Immunoscore“) are prognostic factors independently of the presence of microsatellite instability (MSC)." (PMID 32517213, 2020). "Results in the RANK−/− mouse tumors suggest that up-regulation of negative checkpoints and Tregs occurs as a consequence of a proinflammatory, anti-tumor IFNγ-enriched microenvironment, and may allow RANK−/− tumor cells to evade immune surveillance and grow." (PMID 33303745, 2020). "No detectable shift in fluorescence intensity was observed with any of the tumour cells; a finding that is irrespective of IFNγ pre-treatment to increase HLA-A2 surface expression levels." (PMID 32429338, 2020). "Treatment of tumor cells with CEA-TCB in the absence of immune cells did not lead to PD-L1 upregulation on tumor cells, further confirming the key role of activated immune cells in secreting IFNγ." (PMID 33330050, 2020). "The primary anti-tumor activities of CTL involves their killing of target cells via the exocytosis of cytotoxic granules containing perforin and granzymes as well as the production of cytokines such as IFNγ and tumor necrosis factor (TNF)." (PMID 33013886, 2020). "Notably, we have recently demonstrated that tumor-derived PGE2 drives the nuclear accumulation of p50 NF-κB in CD11b+Ly6G-Ly6Chigh M-MDSC, diverting their response to IFNγ towards NO-mediated immunosuppression and reducing TNFα expression." (PMID 32962159, 2020). "CD8+ T cells from splenocytes of ICT responders produced IFNγ and upregulated CD137 when co-cultured with AB1-HA tumor cells (P = 0.002) and HA peptide (P = 0.007), but minimally with AB1 or MHC-I matched control (RENCA) tumor cells." (PMID 33262762, 2020). "To validate that the deficiency in IFNγ synthesis driven largely by the CpG hypermethylation of the IFNγ promoter and not a general T cell defect, we used the same approach to assess the TNFα kinetics for each tumor-specific CTL clone." (PMID 32194559, 2020). "Furthermore, the Fe3O4-ZnO nanoparticles were observed localizing to draining lymph nodes and inducing anti-tumor immunity, as demonstrated by tenfold increased frequency of spleen CD8+ T cells secreting interferon gamma (IFN-γ) compared to control groups." (PMID 32053995, 2020). "An acquisition of markers associated with T cell exhaustion in cells that are retained within the tumor, indicated by high expression of PD1 Tim3 and CD 39, characterizes lymphocytes that are also unable to produce effector cytokines such as interferon gamma and TNF alpha." (PMID 33203154, 2020). "A previous study suggested an increase in the abundance of AP-1 and an increase in the levels of IFNγ in ER-negative breast cancer, whereas AP-1 levels were not correlated with PR status, tumor grade, tumor size, or lymph node status." (PMID 33102239, 2020). "IFI30, GBP1 and GBP4 were upregulated 2-8-fold (p < 0.0001) in IFNγ positive tumors vs. IFNγ negative tumors in each of the six tumor types." (PMID 32265897, 2020).
tumor (continued). "At 9 days post‐adoptive transfer both tumour and draining lymph node Lck‐Cre;Ptpn2fl/fl OT‐1 T cells were more active, as assessed by the PMA/ionomycin‐induced expression of effector molecules, including IFNγ, TNF and granzyme B." (PMID 31803974, 2020). "Our results demonstrate that tumor endothelial cells contribute to immunosuppressive feed-back loops in response to agonistic CD40 mAb therapy, which restrict the response to immunotherapy through IFNγ-driven expression of IDO1 that inhibits T-cell activation." (PMID 32231867, 2020). "In addition to CD8+ T cells, IFNγ-expressing CD4+ T cells, and NK cells have potent anti-tumor effects in the immune microenvironment." (PMID 32457755, 2020). "Interestingly, both immune cell and tumor cell in the ROIs, low abundance of CD3E and IFNγ, plus IFNγ signature genes were observed." (PMID 33228231, 2020). "Tumor-infiltrating liver MAIT cells showing an exhausted memory effector phenotype accordingly failed to produce IFNγ and cytolytic molecules." (PMID 32053875, 2020). "Co-culture of activated MPE-resident CD8+ T cells with autologous monocytes or tumor containing non-hematopoietic MPE cells did not affect IFNγ production." (PMID 32867034, 2020). "Therefore, the therapeutic use of STAT/JAK-modulators should be carefully evaluated for their specific targeting of STAT3 activity while preserving IFNγ-induced STAT1/2 signaling, which appears to be beneficial for anti-tumor immune responses." (PMID 31766350, 2019). "We also confirmed that IFNγ was present in LLC and CMT167 tumor homogenate." (PMID 31133614, 2019). "As this difference was irrespective of the expression of the IFNγ target PD-L1 on IC, this strongly suggests that expression of this IFNγ response signature originated from tumor cells only and not the immune infiltrate." (PMID 31125352, 2019). "In one HLA-A2− patient sample, some IFNγ releasing response was observed in the IFNγ ELISpot assays, in response to the tumor antigenic peptides, but not to WNF peptide." (PMID 31428094, 2019). "The analysis of memory T cells at day 59 in an independent experiment revealed that most of the M2 specific T cells were effector memory (CD83+CD8+IFNγ+CD44+CD62LLO), thus suggesting that a boost in the immune response could further improve tumor protection." (PMID 30764846, 2019). "Presumably, these proteins suppress IFNγ-induced immunomodulation by dephosphorylating STAT and JAK proteins, as has been reported in CRISPR screens using T-cell coculture systems or syngeneic tumor models." (PMID 31452512, 2019). "T cells can limit tumor cell diffusion by releasing IFNγ, which also affects osteoclastogenesis, indeed lack of IFNγ has been related to the increase of bone metastases." (PMID 30930851, 2019). "We subsequently demonstrated robust anti-tumour functions of CD3-CD56+ NK cells when challenged with each tumour cell line, quantified by CD107a expression on the NK cell surface and intracellular IFNγ production." (PMID 30908480, 2019). "The main sources of IFNγ are CD4+ and CD8+ T cells in the tumor microenvironment, respectively." (PMID 30886199, 2019). "Since Th17 cells could transdifferentiate into interferon-gamma (IFN-γ)-secreting Th1 cells, increased Th17 cells infiltrate into the tumor may promote tumor regression." (PMID 31921642, 2019). "The tumor milieu is already composed of a cocktail of cytokines and chemokines with no IFNγ or bacterial components." (PMID 30925924, 2019). "This was confirmed by in vivo experiments on tumor-bearing mice, where the nanoparticles were able to induce IL-12 production which resulted in increased IFNγ and TNFα in the tumor milieu, thus tumor growth without any sign of systemic toxicity." (PMID 31662751, 2019). "Moreover, the combination enables increased production of IFNγ and GzB by CD8+ tumor infiltrating T cells while augmenting the intra-tumoral presence of NK cells." (PMID 31244820, 2019).